TNF (tumor necrosis factor)
Diseases named in the same sentence as TNF in open-access papers (continued):
Sharing a sentence is not in itself a finding about the gene and the disease.
Sepsis (continued). "In addition, sepsis patients also show higher plasma levels of pro-inflammatory cytokines, including IL-6, IFN-γ, and TNF-α." (PMID 36671034, 2023). "While mHLA-DR, TNF-α secretion, and ALC each show promise as potentially useful biomarkers for sepsis IP, analytic validity of HLA-DR expression and its direct biologic linkage with MNP functional state make it attractive as a potential future gold standard for identification of sepsis IP." (PMID 36825018, 2023). "Compared with wild‐type mice, the TLR4 knockout decreased mortality rates, improved cardiac dysfunction, and reduced expressions of IL‐1β, IL‐6, and TNF‐α in heart tissues and decreased neutrophil infiltration in cecum ligation and puncture (CLP)‐induced sepsis mice." (PMID 38455195, 2023). "ELISA-based detection of the levels of TNF-α, IL-6, and IL-10 in the peripheral blood of mice 24 h after CLP induction revealed that cytokine content in the peripheral blood increased during the development of sepsis." (PMID 37434129, 2023). "When monocytes were challenged with LPS, IL-2, and IFN-γ to simulate sepsis, monocytes that had efferocytosed viable MSC had higher levels of IDO while monocytes that efferocytosed heat inactivated-MSCs produced the lowest levels of TNF-α." (PMID 37592321, 2023). "Some studies in animals have shown that dexmedetomidine could prevent sepsis-induced AKI by reducing the levels of inflammatory cytokines, such as tumor necrosis factor-alpha, monocyte chemotactic protein-1 and interleukin-6, and ameliorate renal dysfunction." (PMID 37596542, 2023). "GAPDH might also affect the inflammatory process through the regulation of tumor necrosis factor synthesis, with GAPDH-mediated proinflammatory cascades occurring after severe injury and sepsis." (PMID 36918848, 2023). "Indeed, using the cecal ligation and puncture (CLP) sepsis model, TLR4 activation increased TNF-α serum levels as early as 4 h after surgery." (PMID 37600769, 2023). "Blockade of TNF-α production with steroids, immunosuppressive drugs, and biological medical products (anti-TNF-α antibodies, etc.)is effective; however, delays in treatment significantly reduce the chance of survival in sepsis." (PMID 37569540, 2023). "Furthermore, sepsis can progress to multiple-organ dysfunction syndrome (MODS), sustained by pro-inflammatory cytokines, such as tumor necrosis factor alpha (TNFα), interleukin-1beta (IL-1β), IL-6, IL-10, and IL-12." (PMID 37298258, 2023). "In mice with SHP2 specifically ablated in macrophages, sCD4 no long improved the survival rates of LPS sepsis, nor inhibited TNF/IL-6 response." (PMID 37332010, 2023). "From a model of MRSA infection for 24h murine sepsis, blood samples showed the vancomycin treatment down regulated Toll-like receptor signaling pathway and IL-1β production, but not IL-6 and TNF-α production." (PMID 36844408, 2023). "While SUL-138 partly limited systemic inflammation demonstrated by lowered plasma IL-6 and TNF-α and dampened a decrease in body temperature during sepsis, it did not mitigate the effects of CLP on white blood cell count." (PMID 37047303, 2023). "DEX treatment counteracted TNFα and LPS downregulation of CD163 and even increased expression above baseline for both treatments, which will be beneficial for both moderate and severe sepsis." (PMID 39619227, 2023). "In this work, attempts were made to identify a diagnostic marker for pediatric sepsis, and the impact of immune cell infiltration on pediatric sepsis was investigated (e.g., coagulation, complement, IL6-JAK-STAT3 signaling, inflammatory response and TNFα signaling via NFκB)." (PMID 37115484, 2023). "Another study considered IL-1β inferior at predicting sepsis when compared to CRP, TNF and IL-6." (PMID 36769133, 2023). "Several biomarkers, although nonspecific, could be used as surrogate markers of the proinflammatory and anti-inflammatory states of sepsis, such as CRP, TREM, TNF-α, IL-6, IL-10 and the TNF/IL-10 ratio." (PMID 37665397, 2023).
Sepsis (continued). "This feedback regulation between cytokines, as well as EFA metabolism, implies that maintaining adequate cell/tissue concentrations of GLA, DGLA, AA, EPA, and DHA is needed to suppress inappropriate and excess generation of IL-6, TNF-α, and that HMGB1 is harmful, especially in sepsis." (PMID 37759732, 2023). "This study showed that C21 might reduce levels of pro-inflammatory cytokines, including TNF-, IL-6, and TNF receptor, by modulating the PI3K/AKT signaling pathways, which can, in turn, reduce renal dysfunction during CLP-induced sepsis in male mice." (PMID 36937479, 2023). "In addition, inflammatory cytokines such as interleukin-1β (IL-1β), IL-6, IL-18, tumor necrosis factor alpha (TNF-α), and interferon-gamma (IFN-γ) have been reported to play an essential role in the development of sepsis and septic shock." (PMID 37359526, 2023). "The results of the current study also confirmed that SIN could induce increased secretion of TNF-α, IL-6, and IL-1β in CLP-induced sepsis." (PMID 37388447, 2023). "Using a sepsis-induced acute lung injury (ALI) model, the authors determined that PDX ameliorated histopathological changes in lung tissue, reduced bacterial load, pulmonary edema, PMN migration, and production of IL-1β, IL-6, TNF-α, and MCP-1." (PMID 37446699, 2023). "(2019) also showed that AST treatment could attenuate inflammatory factors (TNF-α and IL-6) significantly by inhibiting MAPK/NF-κB signaling pathway in a mouse model of lipopolysaccharide (LPS)-induced sepsis and acute lung injury in vitro and in vivo." (PMID 37020589, 2023). "Despite these preclinical results, TNFα inhibition failed to improve survival in sepsis clinical trials, in part, because early TNFα production triggers multifactorial onslaughts leading to HAGMA and AKI." (PMID 37520526, 2023). "During sepsis, activated BMVECs express various adhesion molecules, including CD40, e-selectin, VCAM, ICAM, and inflammatory receptors, such as IL-1, TNF-α and TLR4, which facilitate the infiltration of leukocytes and inflammatory mediators into the brain parenchyma." (PMID 36817492, 2023). "In addition, in another study, we created sepsis by cecal ligation puncture method in rats, TCE significantly reduced TNF-α, IL-1β, IL-6, TOS, OSI levels, expression of caspase-3 and NF κB and increased TAS values." (PMID 37476882, 2023). "The administration of BAM15 particles or BAM15 alone in LPS-induced sepsis mice attenuated inflammatory cytokines (TNF-α and IL-6 but not IL-10) in kidneys." (PMID 38140036, 2023). "The transcription factor, HIF-1α is induced in monocytes from patients with sepsis, and upregulated IRAK3 mRNA and protein expression between 0.5h to 24h as well as reducing TNF-α and IL-6 expression at IT and LT in in vitro monocytes challenged with endotoxin." (PMID 35167625, 2022). "Our study also found that NM exhibits more powerful neutralization for LPS, TNF-α, and CXCL6, which might partly explain the therapeutic advantage of NM over RM in sepsis treatment." (PMID 35345558, 2022). "Although the levels of serum cytokines (tumor necrosis factor [TNF], interleukin [IL]-6, interferon [IFN]-γ, and IL-10) were drastically increased in burn-injured mice under sepsis, pioglitazone reduced the peak level of TNF and continuous production of IL-10 after infection." (PMID 36361535, 2022). "Furthermore, inflammatory cytokines (TNF-α, IL-1β and IL-6) in plasma and bronchoalveolar lavage fluid (BALF) were reduced, representing sepsis-induced inflammatory response was attenuated." (PMID 36030287, 2022). "Conversely, several of these cytokines (IL‐1β, IL‐6, TNF‐α, CXCL1) were significantly elevated in AZ106‐treated mice compared to those subjected to CS alone, indicating a potential role for P2X7R in the modulation of the inflammatory response during sepsis." (PMID 35668576, 2022).
Sepsis (continued). "Moreover, the secretion of PSM-mec toxins increased cytokine expression (IL-1β, TNF-α and the mouse IL-8 homologue CXCL1), leading to elevated sepsis severity in a murine model of sepsis." (PMID 35055041, 2022). "The levels of IL-6, TNF-α, IL-1β, CD4+, and CD8+ in the three groups of patients were compared to analyze the correlation of blood glucose levels with inflammatory response and immune indicators in patients with sepsis." (PMID 35664433, 2022). "In fact, LPS-induced endotoxemia induces arterial hypotension, lactic acidosis, tachycardia, and specific temporal elevations of circulating levels of tumor necrosis factor (TNF)-α, interleukin (IL)-6, and high mobility group box (HMGB)-1, which are important features of sepsis and septic shock." (PMID 35163089, 2022). "TNF-α secretion is limited in LPS-stimulated monocytes isolated from the peripheral blood of sepsis-induced immunosuppressive patients compared with nonseptic patients." (PMID 36209190, 2022). "Among patients admitted for a sepsis (n = 51) or for a non-infectious diagnosis (n = 26), 40 (78.4%) and 18 (69.2%) showed reduced TNF production capacity (≤896 pg/mL), respectively." (PMID 35877767, 2022). "Regardless of the pretreatment they received, sepsis equally increased the mRNA levels of TNF-α, IL-1, IL-6 (p < 0.001) and IL-10 (p < 0.01) in both groups of septic rats." (PMID 35795581, 2022). "On the fifth day of modeling, the levels of IL-1β, IL-6, and TNF-α in the mouse serum were not significantly different between the sepsis and sepsis-AW group but were significantly higher than those in the normal control group." (PMID 36016684, 2022). "In addition, a large number of secretory inflammatory factors such as tumor necrosis factor α (TNF-α) and interleukin-6 (IL-6) are also involved in the sepsis myocardial damage." (PMID 34757596, 2022). "However, treatment with ICOS-Fc significantly decreased IL-1β and TNF-α in WT mice and IL-1β, IL-6 and IL-10 in ICOS-/- mice indicating that ICOS-Fc substantially downmodulates the cytokine storm in sepsis." (PMID 36119089, 2022). "For this, using a well-designed cecal ligation and puncture (CLP)-induced sepsis mouse model, we comparatively measured the level and cost-effectiveness of sepsis biomarkers such as DNI, myeloperoxidase (MPO), procalcitonin (PCT), and tumor necrosis factor-alpha (TNF-α)." (PMID 35334545, 2022). "Moreover, in a murine model of sepsis, administration of miR-181d mimics decreased CD4+ and CD8+ T cells in spleen and lymph nodes and reduced the TNF-α levels in serum." (PMID 35432384, 2022). "However, it is controversial whether TH might trigger infectious complications through a pro-inflammatory effect (including sepsis) or by creating a “sepsis-like” syndrome via an increase in pro-inflammatory cytokines, including interleukin (IL)-1β, IL-8, and tumor necrosis factor (TNF)-α." (PMID 35268485, 2022). "Cucumis melo L.C. Gliadin; SOD extract; Antioxidant; Sepsis model; MDA, TNF-α, Lactate." (PMID 36082333, 2022). "More than 100 clinical trials have been conducted on more than 100 biological agents, including tumor necrosis factor (TNF) and interleukin-1 (IL-1) inhibitors, for the treatment of sepsis, but no specific drugs have been found at present." (PMID 36253831, 2022). "PCT (p=0.019), IL-8 (p=0.039) and TNF-α (p=0.001) were significantly higher in severe sepsis group than mild and non-septic group." (PMID 35898496, 2022). "In addition, MSCs were able to reduce the levels of pro-inflammatory cytokines such as IL-1β, IL-6 and TNF-α and elevate the levels of anti-inflammatory cytokines such as IL-10 and TGF-β in the circulation of aged sepsis model rats." (PMID 35197984, 2022). "Interestingly, expression of inflammatory mediators IL-1β, IL-6, TNFα, iNOS, and COX2 decreased in the presence of a mitoNEET inhibitor, NL-1, or upon expression of mitoNEET shRNA, even in the LPS-induced sepsis model." (PMID 35136051, 2022).
Sepsis (continued). "In recent study in patients with COVID-19 and sepsis, ex vivo stimulation with lipopolysaccharides to trigger TNF-α production by monocytes in presence of rhIL-7 failed to improve the cytokine production." (PMID 36045686, 2022). "LFM-A13 also reduced the histopathological changes and cellular apoptosis in intestinal tissues, inhibited the inflammatory cytokines IL-4, IL-6, and TNF-α in serum and intestinal tissues, and significantly inhibited the increase in intestinal MPO activity induced by burn sepsis." (PMID 35280898, 2022). "Tumor necrosis factor alpha (TNF-α), interleukin 1 beta (IL-1β), and interleukin 6 (IL-6) are important proinflammatory cytokines that are considered the main cytokines in the pathogenesis of sepsis." (PMID 35106183, 2022). "GTS-21, a selective α7nAChR agonist, could lower the expressions of serum tumor necrosis factor (TNF) and high-mobility group box1 (HMGB1) in mice with lethal endotoxemia, sepsis and collagen-induced arthritis." (PMID 35659178, 2022). "After SD, the lung injury score decreased, the NF-κB signaling pathway was inhibited, and the level of TNF-α in BALF decreased, suggesting that the removal of lung sympathetic nerves may attenuate sepsis-induced ALI by inhibiting NF-κB signaling." (PMID 36526959, 2022). "Pathway analysis of upregulated genes revealed that nuclear factor-kappa B (NF-κB), tumor necrosis factor (TNF), Janus kinase (JAK)-signal transducer and activator of transcription (STAT) signaling pathways were enriched in the cluster of sepsis-induced mregDCs." (PMID 35832091, 2022). "Ex vivo LPS treatment of whole blood from patients diagnosed with sepsis resulted in 10–20% decreases of TNF-α and IL-6 production compared to blood from patients without sepsis." (PMID 35167625, 2022). "The median concentrations of TNF-α, IL-6, IL-8, MCP-1, and the chemokine CXCL1 in glioblastoma cyst fluid were far higher than previously published serum values for SARS covid-19 patients, patients with sepsis, and healthy controls." (PMID 35965529, 2022). "Strikingly, the TNF-α levels were still significantly higher at admission in the pre-pandemic group compared to non-COVID-19 sepsis patients during the pandemic (32 ± 144 pg/ml vs 4 ± 5 pg/ml pre-pandemic and pandemic respectively; p < 0.001)." (PMID 34986787, 2022). "Overall, these studies suggest that sepsis after excessive alcohol use not due to lack of inflammatory TNFα signaling." (PMID 35634317, 2022). "The decreased levels of TNF-α and IL-6 revealed the advantage therapy role of GF9 on sepsis." (PMID 36110326, 2022). "Therefore, we further verified the mRNA level of LPIN1 after LPS stimulation and found its expression reduced in the sepsis rat model along with NR8383 and RLE cell lines, which were together with increased TNFα and TLR4 expression." (PMID 35222395, 2022). "Similarly, in the late phase of sepsis (seven days after the surgery), the levels of serum IFN-γ, TNFα, and IL-1β were upregulated in the CLP group compared to the sham group, while the levels of these cytokines were downregulated with cortistatin treatment." (PMID 36148090, 2022). "At present, there are no reports on the diagnostic value of sIL-2R, TNF-α, and PCT in sepsis patients with closed abdominal injury." (PMID 34745113, 2021). "Despite the key pathophysiological role of cytokines during infection, no specific treatment targeting inflammation was shown to be effective in sepsis shock, neither were antibodies targeting TNFα, IL-1, and LPS." (PMID 34804111, 2021). "Moreover, these authors have shown that the anti-histone antibody reduced the mortality of mice in lipopolysaccharide (LPS), TNF, and CLP models of sepsis." (PMID 33732235, 2021). "Studies have shown that the pro-inflammatory cytokines (including TNFα, IL6, and macrophage inflammatory protein 2) secreted by inflammatory cells in sepsis-induced ALI can activate neutrophils and vascular endothelial cells to initiate and maintain pulmonary inflammation." (PMID 34584017, 2021).
Sepsis (continued). "Our study is the first to demonstrate that TLR4 inhibition increased the cell death of stimulated PBMCs in patients with sepsis and this increased cell death was not via TNF/TNF receptor-mediated apoptotic pathway." (PMID 34733114, 2021). "We detected a prominent effect of AE administration downregulating BALF levels of CXCL-1 (P < 0.05), CXCL-8 (P < 0.01), IL-6 (P < 0.05), IL-10 (P < 0.01), and TNF-α (P < 0.001) and upregulating BALF levels of IL-10 (P < 0.05) and IL-1RN (P < 0.05) during sepsis." (PMID 34493741, 2021). "More recently, however, it has been shown that in sepsis, IL-10 may stimulate and oppose IFN-γ and TNF-α production in mononuclear cells and T cells, respectively." (PMID 34938289, 2021). "Overall, all patients had elevated TNF-a and IL-6 levels at initial screening, and most had elevated IL-1β and IL-18, while some had elevated IFN-γ; however, a gradual decrease in levels of all of the cytokines studied was observed upon resolution of sepsis." (PMID 34659208, 2021). "Besides, it also restores the balance of CD4+/CD8+ and Th1/Th2 ratio and reduces the concentrations of IL-6, TNF-α, and HMGB1, thus inhibiting the systemic inflammatory response induced by sepsis to alleviate lung injury." (PMID 34057015, 2021). "Both experimental and clinical studies have shown that there is a significant decrease thanks to plasmapheresis in TNF-alpha, interleukin-6 (IL-6), and endotoxins levels, which play a role in the pathogenesis of systemic inflammatory response syndrome (SIRS) and sepsis." (PMID 33628651, 2021). "TNF-α production was significantly reduced when the PBMCs of the IAI model were stimulated with LPS, and this was significantly prominent in the severe IAI model, indicating increased immune suppression in the severe IAI sepsis model." (PMID 33801494, 2021). "In this experiment, HCAECs were seeded and incubated with isolated and TNF-α activated PBMCs for 1 h with or without pretreatment with sepsis PMPs for 24 h." (PMID 34135769, 2021). "Butyric acid reduces the nuclear NF-κB activity, IL-6 and TNF-α levels, and lung tissue neutrophil infiltration by inhibiting the expression of high mobility group protein 1, TLR4, or histone deacetylase to reduce sepsis-related ALI." (PMID 35003009, 2021). "Many of the measured cytokines/chemokines/immune-modulators were proven to be pathogenic in sepsis and septic shock; however, single targeting of cytokines did not ameliorate sepsis in many trials using anti-TNF, anti-IL-1β, and other cytokines." (PMID 34659208, 2021). "In contrast, SARS-CoV-2 sepsis patients had cytokine concentrations that were elevated versus healthy control subjects during the entire study period, and remained constant or increased during ICU admission, especially TNF-alpha." (PMID 34956225, 2021). "Among the six cytokines that differed significantly between the sepsis and FMF groups, GM-CSF, VEGF, FGF-2, and IL-17A were significantly increased in the FMF group compared with the control group, and TNF-α and MIP-1β were significantly higher in the sepsis group than in healthy subjects." (PMID 34654467, 2021). "The results of the present study were consistent with previous reports, in that IL-6, IL-8, MCP-1, G-CSF, IFN-γ, and TNF-α were higher than in healthy subjects, but IL-18 and IL-17A were not significantly different between healthy subjects and sepsis patients." (PMID 34654467, 2021). "Interestingly, while high-dose EPO attenuated serum cytokines in all sepsis models, low-dose EPO reduced only serum TNF-α and IL-10 in BiNx-CLP mice." (PMID 34831360, 2021). "Quercetin was reported to protect mice from LPS-induced sepsis by inhibiting TNF-α and IL-1β expressions, NF-κB activation, and apoptosis and proposed to prevent myocardial dysfunction through the TLR4/NF-κB signaling pathway during sepsis." (PMID 34938184, 2021). "Studies show TNFα concentration in brain either increases or does not change after induction of sepsis in mice." (PMID 33608025, 2021).